RPS6KA4 (ribosomal protein S6 kinase A4)
Description:
Serine/threonine-protein kinase that is required for the mitogen or stress-induced phosphorylation of the transcription factors CREB1 and ATF1 and for the regulation of the transcription factor RELA, and that contributes to gene activation by histone phosphorylation and functions in the regulation of inflammatory genes. Phosphorylates CREB1 and ATF1 in response to mitogenic or stress stimuli such as UV-C irradiation, epidermal growth factor (EGF) and anisomycin. Plays an essential role in the control of RELA transcriptional activity in response to TNF. Phosphorylates 'Ser-10' of histone H3 in response to mitogenics, stress stimuli and EGF, which results in the transcriptional activation of several immediate early genes, including proto-oncogenes c-fos/FOS and c-jun/JUN. May also phosphorylate 'Ser-28' of histone H3. Mediates the mitogen- and stress-induced phosphorylation of high mobility group protein 1 (HMGN1/HMG14). In lipopolysaccharide-stimulated primary macrophages, acts downstream of the Toll-like receptor TLR4 to limit the production of pro-inflammatory cytokines. Functions probably by inducing transcription of the MAP kinase phosphatase DUSP1 and the anti-inflammatory cytokine interleukin 10 (IL10), via CREB1 and ATF1 transcription factors.
Synonyms: S6K-alpha-4; MSK2; RSK-B
Tractability: Small molecule: a high-quality ligand is known; it belongs to a druggable protein family. PROTAC: it is named in the literature on targeted protein degradation; ubiquitination databases record sites on it; its protein half-life has been measured; a small molecule that binds it is known.
Target class: AGC protein kinase group; AGC protein kinase RSK family; Kinase; AGC protein kinase MSK subfamily; Protein Kinase; Enzyme
Gene: Protein-coding gene on chromosome 11 (64,359,142 to 64,372,215, forward strand). Ensembl gene ENSG00000162302.
Subcellular location: Nucleus
Subcellular location (Human Protein Atlas): Nucleoplasm; Cytosol
Pathways (Reactome):
Developmental Biology: Recycling pathway of L1
Gene Ontology:
Molecular function: ATP binding; histone H3S10 kinase activity; histone H3S28 kinase activity; protein binding; protein serine kinase activity; protein serine/threonine kinase activity; ribosomal protein S6 kinase activity; magnesium ion binding; protein kinase activity
Biological process: interleukin-1-mediated signaling pathway; intracellular signal transduction; positive regulation of transcription by RNA polymerase II; post-translational protein modification; protein phosphorylation; regulation of DNA-templated transcription; negative regulation of cytokine production; TORC1 signaling; chromatin remodeling
Cellular component: nucleoplasm; nucleus; synapse
Genetic constraint (gnomAD): Loss-of-function variants: 38 observed, 79.4 expected, observed/expected ratio (o/e) 0.48, 90% interval 0.37 to 0.63. The upper end of that interval is the gene's LOEUF score, 0.63, which puts it in group 2 of 6, group 1 being the genes least tolerant of losing a copy. Missense variants: 856 observed, 1,012.2 expected, observed/expected ratio (o/e) 0.85, 90% interval 0.8 to 0.89. Synonymous variants: 487 observed, 451.05 expected, observed/expected ratio (o/e) 1.08, 90% interval 1 to 1.16.
Homologues: Orthologues: chimpanzee RPS6KA4 (99% identical), macaque RPS6KA4 (99% identical), pig RPS6KA4 (97% identical), rat Rps6ka4 (96% identical), mouse Rps6ka4 (96% identical), guinea pig RPS6KA4 (95% identical), zebrafish rps6ka4 (68% identical), Caenorhabditis elegans rskn-2 (46% identical), Drosophila melanogaster JIL-1 (41% identical), Drosophila melanogaster S6k (25% identical), Caenorhabditis elegans rsks-1 (24% identical), Caenorhabditis elegans R04A9.7 (19% identical), and 1 more. Paralogues in human: RPS6KA5 (65% identical), RPS6KA3 (39% identical), RPS6KA6 (39% identical), RPS6KA1 (39% identical), RPS6KA2 (39% identical), RPS6KB1 (26% identical), RPS6KB2 (25% identical).
Diseases named in the same sentence as RPS6KA4 in open-access papers:
RPS6KA4 is named in the same sentence as 23 diseases in open-access papers, as found by Europe PMC text mining. Sharing a sentence is not in itself a finding about the gene and the disease. The quoted sentences say what the papers report.
Obesity (2 papers, 2015 to 2023). Accumulation of substantial excess body fat. "Other genes in MAPK signaling that are not significant according to the gene scores (RPS6KA4, DUSP4, MAPKAPK5) have also been associated with obesity." (PMID 37860106, 2023).
hepatocellular carcinoma (1 paper, 2024). A malignant tumor that arises from hepatocytes. "In a study involving hepatocellular carcinoma patients, those with higher expression levels of RPS6KA4 exhibited a poorer survival." (PMID 38287071, 2024).
cancer (9 papers, 2019 to 2025). A tumor composed of atypical neoplastic, often pleomorphic cells that invade other tissues. "RPS6KA4 was considered to play the cancer-promoting effects of HCC32." (PMID 37400463, 2023).
tumor (8 papers, 2010 to 2025). "RPS6KA4 is involved in tumor suppression through epigenetic regulation and interaction with key signaling pathways." (PMID 41463182, 2025). "It has a tumor-suppressive effect and can target RPS6KA4/MSK2." (PMID 35087589, 2022).
RPS6KA4 also shares sentences with these, for which no sentence is quoted: breast carcinoma (3 papers); diabetic nephropathy (2); Alzheimer disease (1); asthma (1); colon cancer (1); craniosynostosis (1); esophageal cancer (1); esophageal squamous cell carcinoma (1); glioma (1); gout (1); infection (1); kidney cancer (1); neurodegenerative disease (1); primary biliary cirrhosis (1); renal carcinoma (1); Salmonella Infections (1); sarcoidosis (1); thyroid cancer (1); Wilms' tumour (1).